TCF3 (transcription factor 3)
Diseases named in the same sentence as TCF3 in open-access papers (continued):
Sharing a sentence is not in itself a finding about the gene and the disease.
cancer (continued). "TCF3, a pivotal transcription factor, serves integral roles in embryonic development, stem cell conservation, and cancer progression." (PMID 40610429, 2025). "This study elucidates, for the first time, the significant associations of TCF3 with DNA variation profiles, prognostic outcomes, and the TME in multiple cancer contexts." (PMID 39205642, 2024). "In the development of cancer, the TCF3 protein, a member of the E protein family of nuclear transcription factors, plays a crucial role in the transcriptional regulation of numerous genes." (PMID 39205642, 2024). "The TCF/LEF family of proteins, with TCF-3 as a notable member, has garnered substantial attention in the field of cancer research due to its pivotal role in tumorigenesis." (PMID 39205642, 2024). "Elevated TCF3 expression is correlated with more aggressive cancer subtypes, as validated by immunohistochemistry and diverse cohort data." (PMID 39205642, 2024). "We demonstrated that TCF3 exerted a significant influence on the prognosis of patients with various types of cancers from the TCGA database." (PMID 39205642, 2024). "This highlights the diverse regulatory functions of TCF3 in various aspects of tumorigenesis and cancer progression." (PMID 39205642, 2024). "Taken together, these findings indicate that TCF3 has a certain impact on the survival of pan-cancer patients and ICI-treated patients." (PMID 39205642, 2024). "Next, we performed an in-depth Kaplan-Meier survival analysis to examine the particular impact of TCF3 on patient survival in various cancers." (PMID 39205642, 2024). "We also provide a previously unrecognized view of the potential synergisms between RUNX3 and CDX2, LHX2 and TCF3 in promoting the transcription of genes involved in cancer stem cell regulation and metastasis." (PMID 38240752, 2024). "Co-expression analyses were carried out across cancers, which clearly revealed that TCF3 was co-expressed with most immune-related genes." (PMID 39205642, 2024). "More specifically, we found that significantly upregulated TCF3 expression was correlated with disease progression, long-term prognosis and suppression of immune stimulatory factors in various cancer types." (PMID 39205642, 2024). "Meanwhile, we found E2F3 (transcription factor 3), which correlated with poor prognosis in a variety of cancers, was negatively regulated HOOK1 transcription though directly binding to the HOOK1 promoter by VHL dependent manner in RCC." (PMID 37085921, 2023). "TCF3 is part of the Wnt pathway-associated TCF/LEF transcription factor family and TCF3 is upregulated in cancers where it promotes proliferation and metastasis." (PMID 36769287, 2023). "It has been shown that TCF3 functions as a key transcription factor in the pathogenesis of several human cancers and plays an important role in stem cell maintenance and carcinogenesis." (PMID 37607071, 2023). "In conclusion, our study indicates that TCF3 has an important function in the development of ESCC and reveals that TCF3 regulates the cancer progression by activating cancer stemness induced by ID1." (PMID 37607071, 2023). "TCF3 had reduced expression in the 6 h RNAseq (log2FC = −0.36) and proteomic (log2FC = −0.89) datasets and is an essential gene in the Cancer Dependency Map." (PMID 36631435, 2023). "Meanwhile, the results of immunofluorescence further confirmed that TCF3 was mostly expressed in nucleus ESCC cells which matched the IHC results of TCF3 in collected carcinoma and paraneoplastic tissues." (PMID 37607071, 2023). "We performed IHC of TCF3 in collected carcinoma and paraneoplastic tissues and found that TCF3 was significantly upregulated in ESCC tissues and mostly expressed in nucleus." (PMID 37607071, 2023). "Silencing of TCF7L1 can significantly inhibit the growth of cancer cells, while overexpression of TCF3 can promote cancer cell proliferation in prostate cancer." (PMID 33824876, 2021).
cancer (continued). "Evidence has demonstrated that TCF3 is recurrently up-regulated in cancers and promotes proliferation and metastasis." (PMID 30988073, 2019). "Among these genes, activating transcription factor 3 (ATF3) plays a central role in the key events triggered by Onconase in treated cancer cells that finally lead to apoptosis." (PMID 28035074, 2017). "On the other hands, expression of ERp29 in this cell type increased the nuclear expression of TCF3, a transcription factor regulating cancer cell differentiation." (PMID 29511484, 2017). "This analysis revealed that activities of TCF3 and E2F6 are associated with cell cycle process indicating a potential function in cancer development." (PMID 27818995, 2016). "The finding of an enrichment in embryonic TFs related to MYC and TCF-3, which are indeed regulators of cancer stem cell pathways, reinforces the TIC identity of the PSs." (PMID 20500816, 2010). "Additionally, TCF3 gene has been shown to promote cancer invasiveness and stemness in different cancer types." (PMID 41150697, 2025). "TCF3 was up-regulated in cancer and enriched in Ca2+ and ferroptosis-related pathways." (PMID 40610429, 2025). "Importantly, TCF3 emerges as a robust predictor of survival across all cancer cohorts and among patients receiving immune checkpoint inhibitors." (PMID 39205642, 2024). "In our study, TCF3 was found to express highly and correlated with cancer stage and prognosis." (PMID 37607071, 2023). "Since IFI6 and IFI27 are downstream targets of activating transcription factor-3 and suppressed to mediate its growth inhibitory actions in cancer cells, it is feasible that the same mechanism mediates the growth inhibitory actions of miR193a-3p in spheroids and needs to be investigated." (PMID 36766731, 2023). "TCF3 performs essential roles in cancer development as the main target gene of Wnt signaling." (PMID 36829181, 2023). "SOX2, UBTF, NFE2L2, TCF3 and STAT3 were underlined as common transcriptional factors, which are responsible for the upregulation of genes involved in processes of the epithelial–mesenchymal transition, cancer stemness, invasion and migration of GBM." (PMID 36231068, 2022). "Overexpression of the TCF3 has been reported in various cancers, including BC and GC." (PMID 34700372, 2022). "While interaction between genes is complex, if a gene is essential to survival of a cancer cell line, we may a priori expect a worse prognosis is likely to be associated with higher expression, as in the case of FLVCR1 and TCF3." (PMID 35882937, 2022). "TCF-3 had been proven to take part in human cancer development and progression." (PMID 34037532, 2021). "The combined analysis of RNA-seq and ChIP-seq for H2A.Z showed downstream gene regulation to mainly occur via the transcriptional misregulation in the cancer pathway, its target genes mainly including TCF3 CDK14, JUP, SPINT1, CDKN1A, and IGF1, each of which corresponded to different cell phenotypes." (PMID 34120148, 2021). "Finally, we observed that basal expression of CSC-related genes (ID1, CD44, HES7 and TCF3) significantly correlate with ONC201 efficacy in >1000 cancer cell lines and combining the expression of multiple genes leads to a stronger overall prediction." (PMID 28767654, 2017). "GFI1, TCF3 and BRCA1are the well-studied in development and cancer." (PMID 24421884, 2014). "Furthermore, we analyzed the effects of CNVs in TCF3 on the prognosis of cancer patients." (PMID 39205642, 2024). "Furthermore, TCF3 was correlated with the expression of cancer stemness markers CD44 and CD133." (PMID 37607071, 2023). "Thus, there is some ambiguity of the role of TCF3 in cancer development." (PMID 34175897, 2021). "This study identifies a new function for class I bHLH transcription factors (e.g., TCF3, TCF4, and TCF12) that are important in cancer and development." (PMID 39119816, 2025). "Heterozygous and homozygous amplification and deletion of TCF4, TCF3, and TCF7 were detected in pan-cancer patients." (PMID 39205642, 2024).
cancer (continued). "Some of the most prevalent included known pediatric cancer fusions RUNX1::RUNX1T1 (15% AML participants), KMT2A::MLLT3/MLLT10 (12% AML), TCF3::PBX1 (4.4% ALL), and ETV6::RUNX1 (2.4% ALL)." (PMID 37323575, 2023). "A pan-cancer view revealed that LEF1, TCF3,TCF4, and TCF7 have aberrant expression andare potentially involvement in the tumorigenesis of various cancer types." (PMID 38100720, 2023). "In mechanism, elevated expression of TCF3 in cancer cells led to the upregulation of Inhibitor of DNA binding 1 (ID1) and finally promoted ESCC cell growth by inducing cancer stemness and enhancing the expression of CD44 and CD133." (PMID 37607071, 2023). "Seven winning TFs (ETV4, ID2, MEIS1, NR4A3, RARA, TCF3, and ZBTB16) are related to transcriptional misregulation in cancer (p-value: 6.9 × 10−5)." (PMID 36101460, 2022). "For samples from Tokyo Children’s Cancer Study Group (TCCSG) biobank, TCF3 was the most prevalent ZNF384 fusion partner." (PMID 33816270, 2021). "We further demonstrate that a SE‐associated ce‐lncRNA, LINC00094 can be activated by transcription factors TCF3 and KLF5 through binding to SE regions and promoted ESCC cancer cell growth." (PMID 32460441, 2020). "Several other upstream regulators appeared to play a role in cell growth, DNA replication, and cancer (CDKN2A, TCF3, PARP1, let-7a-5p)." (PMID 30327482, 2018). "The six selected genes (TWIST1, LAMB1, THY1, EZH2, SALL4, and TCF3) are involved in cell differentiation, HCC cancer stem cells (CSCs) markers, and CSCs involved pathways." (PMID 28158312, 2017). "Furthermore, our findings suggest that TCF3-mediated regulation of TMBIM6 modulates Ca2+-dependent ferroptosis, thereby promoting cancer progression." (PMID 40610429, 2025). "Although it has been suggested that the cryptic exons function to make up the translation frame problem in TCF3-HLF by the cancer cells, there is no functional evidence available to date." (PMID 37019972, 2023). "We then explored by real-time qPCR the impact of miR-662 overexpression in MDA-MB-231 cells on expression levels of well-established stemness markers that are involved in embryogenesis and cancer –NOTCH1, WNT7b, ZEB1, TCF3, CTNNB1, CD44, CD24, SNAI2, OCT-04, c-MYC, EZH2–." (PMID 37443350, 2023). "To investigate whether the HMA-resistance-specific CNAs influence gene expression, we assayed the expression of 8 cancer-related genes by quantitative reverse transcription PCR (RT-qPCR) including BCL9, ARNT, ABL2, STK11, TCF3, SMARCA4, RUNX1, and U2AF1." (PMID 28052028, 2017). "An association between germline mutations of four genes (FLT3, HOXD11, TCF3, and ATP1A1) and cancer has not been reported." (PMID 27701467, 2016). "The evidences here presented suggest that additional genes such as TCF3 and ID1 could also mediate EMT in basal-like carcinomas." (PMID 23555842, 2013). "Furthermore, miR-662 overexpression in MDA-MB-231 cells substantially increased mRNA expression levels of stemness markers involved in embryogenesis and cancer, such as NOTCH1, WNT7b, ZEB1, TCF3, and SNAI2, reinforcing the notion that miR-662 expression enhanced stem-like properties of BC cells." (PMID 37443350, 2023). "In addition, we found that acetylation of H2A.Z in HCC could change the chromatin status and promote the transcription of downstream genes, including TCF3, CDK14, JUP, SPINT1, CDKN1A, and IGF1, which are important regulatory molecules in the cancer misregulation pathway." (PMID 34120148, 2021). "For example, the neo-donor and acceptor sites (in TCF3 locus) in HAL-01 were never found to be utilized from >500,000 RNAseq reads from 9,925 GTEx non-cancer samples." (PMID 37019972, 2023).
infection (16 papers, 2007 to 2025). The state of being infected such as from the introduction of a foreign agent such as serum, vaccine, antigenic substance or organism. "While these comparisons were complicated by the general paucity of detailed annotations of the early response genes, the limited annotations suggest PTCRA is linked to TCF3 in cluster 3, which is up-regulated 1.5 hours post infection." (PMID 18047719, 2007). "To define the mechanism by which β-catenin transcription is inhibited by SARS-CoV-2, we evaluated the impact of infection on transcription factors known to interact with β-catenin: TCF1, TCF3, TCF4, and LEF1." (PMID 41156605, 2025). "By contrast, infection of B cells with both WT and ΔLMP1 EBV genomes led to the downregulation of TCF3 mRNA, which indicates that this event is independent of LMP1." (PMID 28724958, 2017).
hematologic malignancies (2 papers, 2024). "Additionally, TCF-3 plays a critical role in B lymphocyte development and lymphomagenesis, highlighting its involvement in hematological malignancies." (PMID 39205642, 2024).
hematological cancer (1 paper, 2022). "Analysis by LC-MS/MS identified more than 600 Lmo2-interacting molecules in physiological LPs, including the previously reported components of Lmo2 complexes in hematological cancer cell lines, Lyl1, Tal1, Ldb1, Tcf12, Tcf3, and Cbfa2t3 (also known as ETO2 or MTG16)." (PMID 36126774, 2022).
TCF3 also shares sentences with these, for which no sentence is quoted: acute leukemia (3 papers); Autoimmunity (3); esophageal cancer (3); pancreatic cancer (3); acute kidney injury (2); adenocarcinoma (2); Down syndrome (2); dyslipidemia (2); fibrosis (2); multiple myeloma (2); myeloid leukemia (2); osteoarthritis (2); sarcoma (2); Sézary syndrome (2); type 2 diabetes (2); adenovirus infection (1); adrenocortical carcinomas (1); anaplastic large cell lymphoma (1); and heart disorders (1); atherosclerosis (1); autism spectrum disorder (1); autoimmune disease (1); autoimmune enteropathy (1); B cell deficiency (1); bacterial infections (1); bipolar disorder (1); blood cancers (1); brain tumor (1); breast invasive carcinoma (1); cardiovascular diseases (1).
A further 55 diseases each share a sentence with TCF3 in 1 paper.